MED31 (mediator complex subunit 31)
Description:
Component of the Mediator complex, a coactivator involved in the regulated transcription of nearly all RNA polymerase II-dependent genes. Mediator functions as a bridge to convey information from gene-specific regulatory proteins to the basal RNA polymerase II transcription machinery. Mediator is recruited to promoters by direct interactions with regulatory proteins and serves as a scaffold for the assembly of a functional preinitiation complex with RNA polymerase II and the general transcription factors.
Synonyms: SOH1; CGI-125; 3110004H13Rik; SEP10
Tractability: Small molecule: a structure with a bound ligand is known. PROTAC: ubiquitination databases record sites on it; its protein half-life has been measured.
Gene: Protein-coding gene on chromosome 17 (6,643,311 to 6,651,634, reverse strand). Ensembl gene ENSG00000108590.
Subcellular location: Nucleus
Subcellular location (Human Protein Atlas): Nucleoplasm
Pathways (Reactome):
Gene expression (Transcription): Generic Transcription Pathway; MLL4 and MLL3 complexes regulate expression of PPARG target genes in adipogenesis and hepatic steatosis
Developmental Biology: Transcriptional regulation of white adipocyte differentiation
Disease: RSV-host interactions
Metabolism: PPARA activates gene expression
Gene Ontology:
Molecular function: protein binding; transcription coregulator activity; ubiquitin protein ligase activity
Biological process: positive regulation of transcription elongation by RNA polymerase II; positive regulation of transcription initiation by RNA polymerase II; regulation of transcription by RNA polymerase II; RNA polymerase II preinitiation complex assembly; protein ubiquitination; regulation of DNA-templated transcription
Cellular component: core mediator complex; nucleus; nucleoplasm; mediator complex; ubiquitin ligase complex
Genetic constraint (gnomAD): Loss-of-function variants: 11 observed, 22.78 expected, observed/expected ratio (o/e) 0.48, 90% interval 0.3 to 0.8. The upper end of that interval is the gene's LOEUF score, 0.8, which puts it in group 3 of 6, group 1 being the genes least tolerant of losing a copy. Missense variants: 122 observed, 160.72 expected, observed/expected ratio (o/e) 0.76, 90% interval 0.65 to 0.88. Synonymous variants: 60 observed, 56.83 expected, observed/expected ratio (o/e) 1.06, 90% interval 0.86 to 1.31.
Homologues: Orthologues: chimpanzee MED31 (100% identical), macaque MED31 (100% identical), guinea pig MED31 (99% identical), pig MED31 (99% identical), rabbit MED31 (99% identical), mouse Med31 (98% identical), rat Med31 (98% identical), dog MED31 (97% identical), tropical clawed frog med31 (86% identical), zebrafish med31 (81% identical), Drosophila melanogaster MED31 (63% identical), Caenorhabditis elegans mdt-31 (54% identical).
Diseases named in the same sentence as MED31 in open-access papers:
MED31 is named in the same sentence as 9 diseases in open-access papers, as found by Europe PMC text mining. Sharing a sentence is not in itself a finding about the gene and the disease. The quoted sentences say what the papers report.
fungal infection (1 paper, 2020). "In conclusion, the requirement for full Med31 function in host defense against bacterial or fungal infection varies according to the pathogen and the unique suite of host defenses engaged in each case." (PMID 33746938, 2020).
glioma (1 paper, 2025). A benign or malignant brain and spinal cord tumor that arises from glial cells (astrocytes, oligodendrocytes, ependymal cells). "Another circRNA, circ-GLIS3, a miR-548m sponge, is also up-regulated in TMZ-resistant glioma cells and facilitates glioma progression and resistance presumably through the induction of mediator of RNA polymerase II transcription subunit 31 (MED31) expression (a transcription coregulatory)." (PMID 39877636, 2025).
Parkinson disease (1 paper, 2022). A progressive degenerative disorder of the central nervous system characterized by loss of dopamine producing neurons in the substantia nigra and the presence of Lewy bodies in the substantia nigra and locus coeruleus. "The tissue-specific meta-analyses linked Parkinson’s disease to the enhanced expression of MED31 in the female frontal cortex and the dysregulation of 237 genes in the substantia nigra." (PMID 36414996, 2022).
worm infection (1 paper, 2012). "Furthermore, Med31 affects virulence of C. albicans in the worm infection model." (PMID 22496666, 2012).
infection (2 papers, 2012 to 2020). The state of being infected such as from the introduction of a foreign agent such as serum, vaccine, antigenic substance or organism. "At 24 h after infection, the titer was somewhat higher in MyD88 and Med31 RNAi flies than in mCherry RNAi control flies." (PMID 33746938, 2020). "Med30 and Med31 display unique phenotypes, in that they are required for host defense against three types of infections, including E. faecalis and A. fumigatus." (PMID 33746938, 2020). "When challenged with E. faecalis, Med31 RNAi flies displayed a sensitivity to this infection that was intermediate between those of MyD88 and wild-type control flies in seven out of nine experiments, whereas they behaved almost like wild-type flies in the two other experiments." (PMID 33746938, 2020). "Interestingly, we found in nine “natural” infection experiments that Med31 RNAi flies behaved as wild-type control flies in this infection paradigm whereas they displayed a moderate but reproducible susceptibility to injected M. robertsii in five experiments." (PMID 33746938, 2020). "To address whether the role for Med31 in filamentous growth would be important in a disease context, we further tested the ability of med31ΔΔ cells to filament in vivo, using the C. albicans-Caenorhabditis elegans infection model." (PMID 22496666, 2012). "Moreover, Med31 impacts on virulence in an invertebrate infection model." (PMID 22496666, 2012). "We cannot however exclude the possibility that another Mediator subunit mediates an interaction with DIF in the other infections that are not modulated through Med31." (PMID 33746938, 2020). "We found that the C. glabrata burden was not differing between mCherry RNAi and Med31 RNAi flies during the course of the infection." (PMID 33746938, 2020). "Thus, host defense against M. robertsii requires Dif but not necessarily Med31 in the two distinct infection models." (PMID 33746938, 2020). "As Dif has been reported to be required in host defense against M. robertsii in the “natural infection” model, the lack of a requirement for Med31 in this infection is unexpected given its involvement in the host defense against A. fumigatus, E. faecalis, and injected M. robertsii conidia." (PMID 33746938, 2020).
MED31 also shares sentences with these, for which no sentence is quoted: cancer (1 paper); colorectal cancer (1); Li-Fraumeni syndrome (1); pulmonary fibrosis (1).